SNX18 (sorting nexin 18)
Description:
Involved in endocytosis and intracellular vesicle trafficking, both during interphase and at the end of mitosis. Required for efficient progress through mitosis and cytokinesis. Required for normal formation of the cleavage furrow at the end of mitosis. Plays a role in endocytosis via clathrin-coated pits, but also clathrin-independent, actin-dependent fluid-phase endocytosis. Plays a role in macropinocytosis. Binds to membranes enriched in phosphatidylinositol 4,5-bisphosphate and promotes membrane tubulation. Stimulates the GTPase activity of DNM2. Promotes DNM2 location at the plasma membrane. Together with DNM2, involved in autophagosome assembly by regulating trafficking from recycling endosomes of phospholipid scramblase ATG9A.
Synonyms: SH3PXD3B; SH3PX2; SNAG1
Tractability: Antibody: UniProt places it where antibodies can reach, with high confidence; its Gene Ontology location is reachable by antibodies, with medium confidence. PROTAC: ubiquitination databases record sites on it; its protein half-life has been measured.
Gene: Protein-coding gene on chromosome 5 (54,517,727 to 54,546,586, forward strand). Ensembl gene ENSG00000178996.
Subcellular location: Endomembrane system; Endosome membrane; Recycling endosome membrane; Cell membrane; Cytoplasmic vesicle membrane
Subcellular location (Human Protein Atlas): Cytosol
Pathways (Reactome):
Vesicle-mediated transport: Clathrin-mediated endocytosis
Gene Ontology:
Molecular function: phosphatidylinositol-4,5-bisphosphate binding; protein binding; phosphatidylinositol binding
Biological process: cleavage furrow formation; endocytosis; endosomal transport; mitotic cytokinesis; positive regulation of autophagosome assembly; positive regulation of GTPase activity; protein transport; plasma membrane tubulation; mitotic cell cycle; positive regulation of catabolic process
Cellular component: clathrin-coated vesicle; cytoplasmic side of plasma membrane; cytoplasmic vesicle; cytoplasmic vesicle membrane; endomembrane system; endosome membrane; extracellular exosome; plasma membrane; recycling endosome membrane
Genetic constraint (gnomAD): Loss-of-function variants: 34 observed, 41.17 expected, observed/expected ratio (o/e) 0.83, 90% interval 0.63 to 1.1. The synonymous counts are far from expectation, so gnomAD's model fits this gene poorly and the ratio says little. Missense variants: 800 observed, 767.99 expected, observed/expected ratio (o/e) 1.04, 90% interval 0.98 to 1.1. Synonymous variants: 480 observed, 344.31 expected, observed/expected ratio (o/e) 1.39, 90% interval 1.29 to 1.5.
Homologues: Orthologues: mouse Snx18 (96% identical), rat Snx18 (95% identical), pig SNX18 (95% identical), guinea pig SNX18 (93% identical), macaque SNX18 (93% identical), dog SNX18 (90% identical), chimpanzee SNX18 (88% identical), rabbit SNX18 (80% identical), tropical clawed frog snx18 (69% identical), zebrafish snx18a (68% identical), zebrafish snx18b (62% identical). Paralogues in human: SNX33 (49% identical), SNX9 (34% identical), SNX2 (16% identical), SNX1 (16% identical), SNX30 (16% identical), SNX7 (16% identical), SNX8 (15% identical), SNX4 (13% identical), SNX6 (12% identical), SNX5 (11% identical), SNX32 (10% identical), SNX12 (8% identical), and 3 more.
Diseases named in the same sentence as SNX18 in open-access papers:
SNX18 is named in the same sentence as 7 diseases in open-access papers, as found by Europe PMC text mining. Sharing a sentence is not in itself a finding about the gene and the disease. The quoted sentences say what the papers report.
breast carcinoma (1 paper, 2025). "On the other hand, it has been shown that SNX9, which is closely related to SNX18, is expressed at decreasing levels with cancer progression and in general in tumor tissue, pointing towards its tumor suppressive functions in breast cancer." (PMID 40805149, 2025).
ischemic stroke (1 paper, 2023). A stroke disorder caused by obstruction of blood flow to the brain, due to thrombotic (local blood clot formation) or embolic (due to a blood clot or other material traveling from another site) event. "Interestingly, methylation at cg18373318 (SNX18) has been previously shown to be associated with ischemic stroke by a previous EWAS; ischemic stroke is one of the multiple cardiovascular outcomes observed in individuals with obesity." (PMID 37393279, 2023).
cancer (2 papers, 2019 to 2025). A tumor composed of atypical neoplastic, often pleomorphic cells that invade other tissues. "All in all, we believe that miR-218-5p takes part in the starvation-induced autophagy response, regulating the expression of SNX18 among other autophagy-associated proteins, and this pathway is an important protective factor, allowing cancer cells to survive under nutrient scarcity." (PMID 40805149, 2025). "Starvation induces BC-specific miRNA dysregulation, affecting particularly miR-218-5p, which acts via SNX18, promoting the cancer cells’ survival." (PMID 40805149, 2025). "The study of miR-218-5p molecular targets has shown that its inhibition of sorting nexin 18 (SNX18) may act as an important regulator of the starvation-induced response in cancer cells." (PMID 40805149, 2025). "We believe that SNX18 may act as the most important target of miR-218-5p in cancer cell starvation response, and its inhibition may regulate cell trafficking, protecting the cancer cells from autophagy overactivation in nutrient-deprived conditions." (PMID 40805149, 2025). "Thus, N-WASP forms a complex with Snx18 on endocytic tubules mediating LPAR1 recycling and having strong implications for chemotactic signaling and cancer cell invasion." (PMID 31668663, 2019).
tumor (2 papers, 2024 to 2025). "Subunit E1 of 2-oxoglutarate dehydrogenase (OGDH-E1) was the best classifying factor for the superficial tumor region, while sorting nexin-18 and coatomer-beta protein (beta-COP), implicated in protein trafficking, classified the deep region." (PMID 39195201, 2024). "Among those here identified, sorting nexin-18 was the only isoform showing significant variations in the tumor samples." (PMID 39195201, 2024). "Among them, sorting nexin-18 and GRASP-1 were the only proteins with significantly different levels between the surface and the deep part of the tumor." (PMID 39195201, 2024). "Like sorting nexin-18, PYY was never detected in the deep region of the tumor and was identified as a less-abundant protein in superficial tumor tissue." (PMID 39195201, 2024).
infection (1 paper, 2017). The state of being infected such as from the introduction of a foreign agent such as serum, vaccine, antigenic substance or organism. "To examine the kinetics of SNX18 recruitment during early stages of infection, we next measured the amount of EGFP-SNX18 at the plasma membrane and cytosol at various time points post infection by quantitating the fluorescence density profiles of selected regions of interest." (PMID 28664153, 2017). "To investigate the dynamics of SNX18 recruitment to the plasma membrane during S. Typhimurium internalization, we performed live imaging of EGFP-SNX18-expressing HEK293 cells within the first 10 min of infection." (PMID 28664153, 2017).
SNX18 also shares sentences with these, for which no sentence is quoted: Obesity (1 paper); pancreatic cancer (1).